HSF1 (heat shock transcription factor 1)
Diseases named in the same sentence as HSF1 in open-access papers (continued):
Sharing a sentence is not in itself a finding about the gene and the disease.
cancer (continued). "High expression of HSF1 has additionally been associated with cancer stem cells, as well as drug resistance." (PMID 34439354, 2021). "As HSF1 has been implicated in several cancer types, it has been proposed as a potential anti-cancer therapy target." (PMID 34439354, 2021). "Resistance to proteasome inhibitors have been reported in patients, and this is either brought about by cancer mutations in the proteasome core or via upregulation of HSF1-mediated proteotoxic response pathway." (PMID 33376136, 2021). "Targeting HSF1 is a potential strategy for the management of human cancers associated with activated WNT/β-catenin signaling." (PMID 32838807, 2020). "The second study showed that cancer-associated fibroblasts (CAFs) require HSF1 for transcriptional reprogramming of the stroma." (PMID 32408596, 2020). "Compared to the most frequently mutated genes across these cancer types, the incidence of HSF1 missense mutations, frame shifts, splice site abnormalities, or frame deletions were minimal." (PMID 32331382, 2020). "Another mechanism involves the binding of HSF1 phosphorylated at serines 303 and 307 to the ubiquitin ligase FBXW7: Loss of this factor in cancer is associated with an amplification of HSF1 levels and increased metastasis." (PMID 32331382, 2020). "Expression and activation of Heat shock factor 1 (HSF1) in cancer associated fibroblasts have been associated with protumorigenic functions." (PMID 33288768, 2020). "Next, whole-exome sequencing efforts suggest the need to explore the role of genetic variation within the HSF1-signaling axis in predisposing individuals to cancer." (PMID 32331382, 2020). "Ontological analysis of the novel group of genes associated with HSF1 and transcribed in cancer cells with a metastatic phenotype included Ly6K and prominin 2, which are associated with stem cell properties and metastasis." (PMID 32331382, 2020). "HSF1 is encoded at chromosome 8q24.3, a genomic hotspot for several cancers, including prostate, liver, and bladder." (PMID 32331382, 2020). "Cancer‐associated fibroblasts (CAFs) show hyperactivated HSF1, which reprograms tumor stroma and promotes tumor malignancy." (PMID 32691951, 2020). "Abnormally increased HSF1 is frequently observed in multiple types of cancer, including HCC, and is associated with invasion and metastasis, and thus it is considered to be a prognostic marker of HCC." (PMID 31540279, 2019). "Numerous clinical and basic research studies showed that high expression level of HSF1 is associated with poor outcomes in many cancer types, pointing out the potential of HSF1 as a prognostic biomarker." (PMID 31699156, 2019). "After multiple testing corrections, we found 114 genes associated with HSF1 expression (p < 0.05), and only 17 anti-correlated genes (p < 0.05) for all cancer types." (PMID 31699156, 2019). "HSF1 affects many aspects of cellular metabolism that are important for the cancer phenotype: it modulates signaling pathways associated with growth and proliferation, apoptosis, glucose metabolism, angiogenesis, and cell motility." (PMID 31614463, 2019). "The heat-shock transcription factor 1 (HSF1) has been linked to cell proliferation and survival in cancer and has been proposed as a biomarker for poor prognosis." (PMID 31699156, 2019). "Given the growing body of evidence linking Hsf1 activity to numerous diseases associated with proteotoxic stress, but also rapid cell growth in cancer, it will be of great interest to challenge this model in the future." (PMID 31124783, 2019). "Comprised of over 500 genes, this cancer-specific HSF1 transcriptome is associated with poor clinical outcomes." (PMID 29725069, 2018).
cancer (continued). "HSF1-CanSig genes function and operate differently than typical cancer-causing genes, yet it is involved in fundamental oncogenic processes." (PMID 29268782, 2017). "HSF-1 is associated with tissue-specific tumorigenesis in a number of mouse models, and has been used as a prognostic marker of cancer types." (PMID 29348836, 2017). "We therefore analyzed the correlation between IER5 mRNA levels and the expression of cancer-associated HSF1 target genes in cancer patients." (PMID 26754925, 2016). "Via HSF1 knockdown and colony formation assays, we show that HSF1 promotes the ability of cells to grow under conditions of low cell density, a hallmark of cancer cells." (PMID 27997575, 2016). "This makes HSR1 an interesting pharmacological target for various conditions associated with HSF1 activation, such as inflammation, ischemia/reperfusion, and cancer." (PMID 26509637, 2016). "This is strikingly demonstrated in studies that have deleted HSF1 from mice carrying cancer-promoting mutations." (PMID 26320184, 2015). "Recently, studies have revealed that HSF1 not only drives transcription in cancer cells but is also capable of reprogramming transcription extensively in cancer-associated fibroblasts (CAFs)." (PMID 26511079, 2015). "We suggest that the early activation of this Hsf1 dependent cell stress pathway by mono-allelic mutations in APC can affect cell programming in a way that contributes to cancer onset." (PMID 26320184, 2015). "As a result, HSF1 both facilitates initial oncogenic transformation and maintains the malignant phenotype of established cancer cell lines driven by a wide range of mutations." (PMID 26359349, 2015). "As with both Hsp90 and Hsf1, mTOR is often overactivated in cancer; certain gain of function mutations in the mTOR kinase domain being tumorigenic in animal models." (PMID 24970820, 2014). "The deacetylase sirtuin-1, a factor associated with cancer, promotes deacetylation of HSF1 to activate it." (PMID 25147790, 2014). "An association of HSF1 with cancer initiation and development has been found in animal models and human cancer tissues." (PMID 25199534, 2014). "Curiously, maladaptation not only includes the role of the HSF1-Hsp90 axis in supporting proliferation of cancer cells, a pathogenic state, but also the propagation and resistance of viral pathogens to host defenses that can impact human health." (PMID 25406061, 2014). "HSF1 knockdown didn't affect the percentage of cancer cells in cell cycle while HSP90 inhibitor caused more cancer cells into S+G2M phase (data not shown)." (PMID 23615731, 2013). "For example, HSF1 (heat shock transcription factor 1) has been associated with cancer in various ways." (PMID 23468608, 2013). "Curiously, although both diseases are associated with advancing age, HSF1 loses activity in the progression of neurodegenerative diseases while being activated in cancer." (PMID 21085490, 2010). "Previous studies suggested that the level of HSF1 become elevated in a number of cancer cells, and the elevated HSF1 is implicated in tumorigenesis through the expression of the HSP70 family proteins and the inhibition of apoptotic pathways." (PMID 20537126, 2010). "HSF1 further supports malignancy by non‐cell‐autonomous mechanisms, where it regulates gene expression in cancer‐associated fibroblasts (CAFs) to alter the tumor microenvironment by extracellular matrix (ECM) remodeling and by the secretion of signaling molecules that promote cell proliferation." (PMID 40457168, 2025). "In addition, due to the close association between HSF1 expression level and prognosis, it has been served as a prognostic biomarker and a potential target for cancer treatment." (PMID 40424327, 2025).
cancer (continued). "Moreover, in vitro and in vivo approaches indicated that inactivation of HSF1 is highly detrimental to the growth of iCCA cell lines, cancer-associated fibroblasts, tumor organoids, and biliary tumors developed in mice." (PMID 39243039, 2024). "HSF1’s involvement in malignant transformation underscores its crucial role in mitigating stresses associated with increased protein synthesis and genomic instability in cancer cells." (PMID 39495731, 2024). "In addition, the impact of HSF1 suppression on tumor cells and tumor stroma was assessed in iCCA cell lines, human iCCA cancer-associated fibroblasts (hCAFs), and patient-derived organoids." (PMID 39243039, 2024). "Therefore, the importance of HSF1 supporting carcinogenesis can be demonstrated by the susceptibility reduction of HSF1-KO cells to cancer formation." (PMID 38589452, 2024). "Accumulating evidence has demonstrated that the HSF1-regulated proteostatic capacity of cells is closely associated with cancer development, progression, and chemoresistance, leading to poor clinical outcomes in patients with cancer." (PMID 38474017, 2024). "However, the relationship between HSF1 activity and organismal health is complex, with increased HSF1 activity also associated with cancer cell survival and tumorigenesis." (PMID 38164224, 2023). "In brief, a condition of oxidative stress could be indirectly related to the development of cancer in NF1-deficient cells by the increased activity of HSF1." (PMID 37627552, 2023). "HSF1-associated ncRNAs were found in different types of cancers." (PMID 37153737, 2023). "Loss of HSF1 delays or prevents formation of multiple cancer types." (PMID 35080342, 2022). "In addition, various studies revealed that HSF1 is associated with metastasis, cancer cell survival, and tumor proliferation." (PMID 35990198, 2022). "Notably, HSF1 is closely associated with metabolism reprogramming, which is considered to be one of the hallmarks of cancer." (PMID 36010849, 2022). "Among the many functions of HSF1 in cancer, this increase could, in part, underlie the high dependence on HSF1 for LSC self-renewal." (PMID 36245043, 2022). "Thus, HSF1 is considered a diagnostic and prognostic biomarker, and it is currently being targeted to develop new cancer therapies." (PMID 33675143, 2021). "Considering that the high expression of HSF1 in various types of cancers are frequently associated with poor prognosis and resistance for chemotherapy, the sensitizing effects of KRIBB11 on the suppression of cancer cell growth appear to be a promising therapeutic strategy for clinical application." (PMID 34299435, 2021). "In addition, scRNA-seq revealed upregulation of several cancer-associated (Il-4/Il-13, Hsf1/HSP), oncogenic (TGFβ, NGF, FGF, MAPK) and self-renewal (Wnt, Notch) pathways in p63+/−;ErbB2 luminal cells and PIMECs per se." (PMID 34023861, 2021). "HSF1 is significantly upregulated in various common cancers, and it is associated with prognosis." (PMID 34239690, 2021). "Interestingly, HSF1 overexpression is associated with resistance to various treatments and poor prognosis in most of these cancers." (PMID 33593922, 2021). "High HSF1 expression has been associated with poor survival in cancer patients." (PMID 34064083, 2021). "Alterations in HSF1 function impact protein homeostasis and are strongly linked to diseases, such as neurodegenerative disorders, metabolic diseases, and different types of cancers." (PMID 34198675, 2021). "Thus, although HSF1 mRNA levels were almost universally elevated across cancer types in the TCGA datasets, genetic mutation was rare in the tumors studied." (PMID 32331382, 2020).
cancer (continued). "HSF1 can associate with the NuRD complex as well as complexes containing the histone acetylase p300 and it would be informative to determine potential roles for these factors in HSF1 functions in cancer at the level of histone modification." (PMID 32331382, 2020). "Interestingly, cancer genomics revealed mutations in Hsf1 that according to the Hsp70 binding score algorithm would be expected to lower the affinity of Hsc70 for Hsf1." (PMID 32490574, 2020). "However, the primary causes for altered HSF1 activity and expression in cancer remain to be fully established." (PMID 32331382, 2020). "Overexpression of HSF1 has been linked with cancer proliferation, and malignancy, suggesting that HSF1 could serve as a prognostic marker." (PMID 31699156, 2019). "Despite that the here identified hyper-stress program in yeast involves other gene targets than the mammalian programs, we speculate that the fundamental mechanism of chaperone titration may underlie the expanded Hsf1 regulons in both yeast and cancers." (PMID 31552827, 2019). "Thus all ways of HSF1 down-regulation cause the suppression of cell proliferation and this phenomenon is proved for cancer cells of different origin highlighting the anti-tumor directivity of the protein inhibitors like CL-43." (PMID 29930764, 2018). "HSF1 is a transcription factor that controls a broad spectrum of pro-survival events essential for protecting cells from proteotoxic stress, which is caused by the accumulation of misfolded proteins in cancer cells." (PMID 29799521, 2018). "Recently, the key role of HSF1 was recognized to play a role in aging and oncogenesis, where its accumulation and activation is triggered by proteotoxic stress or oncogenic stress (cellular or environmental stresses associated with cancer)." (PMID 28257109, 2017). "HSF1 has been implicated in tumorigenesis and the progression of several cancers." (PMID 28783244, 2017). "As a transcription factor, HSF1 controls a broad spectrum of events essential for protecting cells from proteotoxic stress, which is associated with the accumulation of misfolded proteins, e.g. in cancer cells." (PMID 27791982, 2017). "While little is known about TANC1, HSF1 is a heat-shock protein previously reported to be associated with carcinogenesis and poor prognosis, as well as supporting malignancy in a variety of cancers." (PMID 26388441, 2015). "This hypothesis predicts that cancer driver mutations will result in chronic activation of the HSF1 cell stress pathway prior to cancer onset to allow cells to tolerate additional genomic instability and thus contribute to cancer progression." (PMID 26320184, 2015). "HSF1 overexpression in cancer was first noticed 14 years ago, then its elevated expression was linked with higher malignancy, potential to metastasis, and a reduced survival rate of cancer patients." (PMID 24467529, 2014). "It is important to develop strategies for the inhibition of Hsf1, since this transcription factor is a driver of cancer progression and the Hsf1-directed heat shock response frequently causes a degree of resistance to Hsp90 inhibitor cancer drugs (see Introduction)." (PMID 24970820, 2014). "Its strong association with the malignant phenotype implies that HSF1 antagonists may have general and effective utilities in cancer therapy." (PMID 24800749, 2014). "Moreover, it has been shown that increased HSF1 expression is associated with reduced survival of cancer patients." (PMID 24165036, 2013). "Thus, HSF1 induces repression of estrogen-dependent gene transcription, an effect linked to cancer invasiveness." (PMID 24212658, 2011). "(A possible shortcut to such a lengthy program could be to use the sequencing data accumulated in the search for alleles that raise susceptibility and look for polymorphisms in human HSF1 that are rare in old people who have had cancer)." (PMID 21489209, 2011).
cancer (continued). "However, the question remains whether elevated HSF1 activity in tumors is solely a response to proteotoxic stress associated with cancer or if its expression and activation are directly regulated by oncogenic signaling." (PMID 40287736, 2025). "Additionally, HSF1-associated non-coding RNAs have been identified in various cancer types." (PMID 38748048, 2024). "Heat shock factor 1 (HSF1) may cause HSF1-driven pro-tumorigenic program in cancer cells." (PMID 36578079, 2022). "Furthermore, high levels of HSF1 expression associate with poor outcome of various cancers." (PMID 33376136, 2021). "Importantly, this new link between DYRK2 and HSF1 appears to be relevant in TNBC patients as DYRK2 levels correlate positively with HSF1 nuclear levels, and negatively associate with cancer-specific survival and time to recurrence, supporting a pro-tumoural role for DYRK2 in TNBC." (PMID 33268814, 2021). "Moreover, cancer cells are easily mutated and exhibit high expression and activity of HSF1." (PMID 34064083, 2021). "Moreover, HSF1 is associated with neurodegenerative diseases and cancers." (PMID 34439354, 2021). "Another experimental work elucidated the functional interrelation between NRF2 and heat shock factor-1 (HSF1), a protein that is frequently overexpressed and implicated in the survival and proliferation of cancer cells, also correlated with a poor prognosis of cancer patients." (PMID 33805996, 2021). "We investigated the role of DHX8 in regulating HSF1 within the broader context of DHX8 function in cancer cells." (PMID 41837178, 2026). "Our analysis across TCGA cancer cohorts also observed several cancer types for which HSF1 has significant copy-number gain, with the highest frequency of amplification (≥2 copy-number gain) in the cohort of patients with HGSOC." (PMID 39831777, 2025). "HSF1 is further incorporated in cancer metabolism by positively regulating biosynthesis of mevalonate and cholesterol." (PMID 40287736, 2025). "As previously discussed, HSF1 is overexpressed in various cancers and plays a key role in tumorigenesis." (PMID 40287736, 2025). "Dysregulated cell division is an ever-present phenomenon spanning multiple hallmarks of cancer and over the years, HSF1 has emerged as a critical and multifaceted regulator of mitosis." (PMID 40287736, 2025). "Despite its importance in cancer biology, efforts to target HSF1 therapeutically remain in preclinical stages, with most approaches facing significant limitations." (PMID 40287736, 2025). "Here, we added another line of evidence supporting the role of HSF1 as a metastasis-promoting factor in cancer progression." (PMID 41028522, 2025). "HSF1 drives a transcriptional program in cancer cells that is different from the canonical heat shock response." (PMID 40002205, 2025). "HSF1 is a major regulator of the heat shock response, which can program the stromal cells of the tumor, thereby promoting the formation of malignant tumors." (PMID 40399470, 2025). "Dysfunction of HSF1 contributes to the pathogenesis of a spectrum of acute and chronic diseases, including cancer." (PMID 40520012, 2025). "mTOR is crucial for the activation of HSF1 and the synthesis of HSP90, and the activation of HSF1 and the synthesis of HSP90 in many cancers are significantly associated with tumor metastasis and death." (PMID 41001347, 2025). "These interactions suggest a complex regulatory network involving HSF1, which is consistent with its pivotal role in driving the proliferation and growth of cancer cells." (PMID 40520012, 2025). "By integrating the latest research, it seeks to unravel the complexities of HSF1 in cell division and cancer biology, offering a foundational understanding for both curious readers first exploring the topic and seasoned researchers in the field." (PMID 40287736, 2025).